TNF (tumor necrosis factor)
Diseases named in the same sentence as TNF in open-access papers (continued):
Sharing a sentence is not in itself a finding about the gene and the disease.
colitis (continued). "Mice with colitis, regardless of diet, presented higher concentrations of all measured cytokines (TNF, IL-6, IL-4, IL-10, IFNy), and MCP-1/CCL2." (PMID 22073943, 2011). "Meanwhile, the levels of colonic TNF-α, IL-6, and IFN-γ in colitis mice were significantly higher than that in control mice, and treatment with AMD3100 markedly reduced the cytokines levels in colitis mice." (PMID 22073304, 2011). "To determine whether LITAF participates in the mediation of TNF-α expression in acutely inflamed colonic tissues, we first established the TNBS-induced colonic inflammation model in C57BL/6 mice." (PMID 21984950, 2011). "In both models, ciprofloxacin failed to protect against development of colitis and failed to attenuate colonic influx of neutrophils or expression of signature cytokines such as TNFα and IL-1β in a GP-BAR1-dependent manner." (PMID 22046243, 2011). "The aims of this study were to investigate the effects of punicic acid on TNFα-induced ROS over-production by human neutrophils and to evaluate the effect of punicic acid in a rat model of 2, 4, 6-trinitrobenzenesulfonic acid (TNBS)-induced colitis." (PMID 19649246, 2009). "However, a fraction (40–50%) of the double knockout mice (TNFR1KO/ TAK1IEKO) developed ileitis and colitis around the age of 14–17-days-old, suggesting that TAK1 is also important for preventing TNF-independent inflammation." (PMID 19234607, 2009). "While TNF-α produced by CD4+ T cells is neither sufficient nor required for the induction of murine colitis, its production by Ag-presenting cells is essential for the histopathological and clinical signs of colitis." (PMID 18533024, 2008). "Taken together, these data demonstrate that severe colitis can occur in the absence of T and B cells and without systemic or local colonic or stool elevations in TNF." (PMID 18331642, 2008). "Colonic levels of TNF were elevated in untreated IL-10-/- mice with colitis compared with wild type mice without colitis." (PMID 18331642, 2008). "The colonic TNF content of these mice was statistically similar to that present in non-DSS-exposed mice without colitis (data not shown)." (PMID 18331642, 2008). "The colitis, developed after TNBS administration, largely enhanced the expression of TNF-α, IL-6, IL-1β, IL-12, IL-23, IL-17, Cox-2, IL-10, and IFNβ genes, with a fold increase in mRNA levels of 28.7, 89.26, 303.9, 36.03, 9.14, 329.00, 32.07, 10.89, and 24.16, respectively compared to healthy mice." (PMID 17375199, 2007). "In conclusion, pro-inflammatory cytokines IL-1β and TNFα are considered to be primary mediators, whereas PAF, eicosanoids and NO may reflect secondary mediators in experimental colitis." (PMID 18475637, 1995). "In this study, we found that EcNΔlpp::A5‐aTN can neutralize TNF‐α and cooperatively ameliorate inflammation by inhibiting ROS/JNK/p38/Caspase‐8/Caspase‐3‐mediated apoptosis, upregulating tight junction proteins, and modulating the immune‐microbiome balance in mice with colitis." (PMID 41017573, 2025). "Furthermore, the SOD3-mediated, anti-inflammatory role in skin inflammation by inhibiting the expression of proinflammatory cytokines, including TNF-α, IL-1β, IL-6, and IL-8, and SOD1-mediated suppression of proinflammatory immune responses against oxidative stress in colitis, were also reported." (PMID 40825682, 2025). "However, other work using a DSS-only model of colitis found that, while 5% (w/w) cocoa-enriched diet decreased oxidative stress and TNF-α levels, it did not significantly alter clinical or histological signs of colitis in rats." (PMID 40806068, 2025). "Furthermore, in a DSS‐induced colitis mouse model, UMSC treatment decreased the proportion of Th1 and Th17 cells and down‐regulated the expression of inflammatory cytokines, including IFN‐γ, IL‐1β, IL‐6, IL‐17, as well as TNF‐α at the mRNA levels." (PMID 40842289, 2025).
colitis (continued). "Therefore, our study revealed that the abundance of F. nucleatum in tissues might be correlated with the response of patients with UC to anti‐TNF therapy and that F. nucleatum could inhibit the responsiveness of DSS‐induced colitis mice to anti‐TNF therapy." (PMID 39739648, 2025). "Indeed, CRIF1 overexpression reduced the numbers of cells expressing TNF-α, TNFR1, RIPK1, RIPK3, and phosphorylated MLKL in our experimental mice, suggesting that CRIF1 overexpression can downregulate intestinal inflammatory cell death in colitis." (PMID 40821844, 2025). "The relative mRNA expression of pro-inflammatory factors (IL-1β, TNF-α, and IL-18) was significantly increased in the DSS group compared to the CON group (p < 0.05), indicating a disruption in the balance of inflammatory factors and impaired intestinal immunity in the colitis mice." (PMID 41227621, 2025). "While it has been used to induce colitis and oral inflammation in animal models, high concentrations of acetate demonstrated protective effects in a patient-derived human epithelial cell culture model, including improved epithelial resistance and reduced expression of IL8 and TNFα." (PMID 40647225, 2025). "Hence, the findings of this study support the hypothesis that PTX attenuates SPHK1/S1P signaling via inhibition of TNF‐α and activation of the cAMP/PKA axis, contributing to its anti‐inflammatory effects in colitis." (PMID 40387460, 2025). "Moreover, the results of network pharmacology have validated existing literature and our experimental findings, thereby confirming the TRPM8 signaling pathway and inflammatory factors such as TNF-α, IFN-γ, and IL-6 as pivotal components in the regulatory role exerted by COP on DSS-induced colitis." (PMID 40053041, 2025). "Although previous studies have examined the effects of RES on inflammatory signaling pathways and TNF-α in IBD models, our study adds a novel layer by specifically characterizing the expression of TNF receptors (TNFR1 and TNFR2), using immunofluorescence in a TNBS-induced colitis model." (PMID 40565241, 2025). "Interestingly, orally administered MEs carrying TNF-α siRNA could effectively reach colonic tissues and reduced TNF-α expression, thereby and alleviating colitis symptom in a murine model." (PMID 38951872, 2024). "In alcohol-induced colon inflammation, a polyphenol-rich extract of Zhenjiang aromatic vinegar was shown to increase IL-10 and IL-22 levels in the colon of ICR (Institute of Cancer Research) mice exposed to ethanol and also to reduce TNF-α, IL-6, IL-1β, and LPS levels." (PMID 38247489, 2024). "In this study, the authors created a model of colitis that did not respond to TNFα, thereby demonstrating that IL-1β expression was another major pathway in the progression of colitis, thus highlighting the importance of IL-1β in UC patients that do not respond to TNFα inhibition." (PMID 39201260, 2024). "Furthermore, animal studies demonstrated that IFN-γ-producing cytotoxic CD8+ T cells could promote development of colitis through secretion of IFN-γ and TNF-α and their detrimental effects on intestinal epithelial cells." (PMID 39464882, 2024). "SP could ameliorate colitis and intestinal epithelium disruption in DSS-induced mice, and the in vitro inflammation model of tumor necrosis factor-alpha (TNF-α)-stimulated human colon carcinoma cell line (Caco-2), which was dependent on its specific receptor NK1R." (PMID 38725846, 2024). "To explore the response of DRGs to biologic therapies, such as TNF-α inhibitors golimumab (GLM), infliximab (IFX), and vedolizumab (VDZ), we analyzed the GSE92415 and GSE73661 datasets, which include colon biopsy samples from patients with moderate to severe colitis." (PMID 39769269, 2024).
colitis (continued). "Furthermore, protocatechuic acid-treated mice exhibited a reduction in the expression of proinflammatory cytokines (IL-6, IL-1β, TNF-α, and cyclooxygenase 2 (COX-2)) in TNBS-induced colitis, achieved by modulating the sphingosine kinase (SphK)/S1P and related signaling pathways." (PMID 38732594, 2024). "Chlorogenic acid, at concentrations of 1 mM or 20 mg/kg, markedly reduced the release of IFN-γ, TNF-α, and IL-6 and the infiltration of F4/80+ macrophages, CD3+ T cells, and CD177+ neutrophils into the colon by blocking the activated NF-κB signaling pathway in DSS-induced colitis." (PMID 38732594, 2024). "Our results demonstrated that the cecal gene expression of IL-6, CXCL2 (murine IL-8 homologue), IL-1β, TNF-α, IL-17a, IL-22, and CRAMP (homologue of human cathelicidin LL-37) was significantly elevated in the mice with P. aeruginosa-infected colitis after chemotherapy." (PMID 38397855, 2024). "Likewise, a previous report showed that Ly6Chi M-MDSCs during colitis extensively invaded the colon and switched from regulatory macrophages (MPs) to pro-inflammatory CD103−CX3CR1intCD11b+ DCs, producing high levels of IL-12, IL-23, iNOS, and TNF." (PMID 37733169, 2024). "In addition, other authors also demonstrated that a new polysaccharide isolated from HE (HEP10) suppressed the LPS/DSS-induced production of iNOS and COX-2 and proinflammatory mediators such as TNF-α, IL-6 and IL-1β, as well as NLRP3 inflammasome, in rodent models of colitis and in macrophages." (PMID 38671931, 2024). "The PCA has been reported to inhibit the production of inflammatory mediators, such as IL-6, TNF, IL-1β, and prostaglandin E2 (PGE2), potentially by suppressing the activation of NF-κB and extracellular signal-regulated kinase (ERK) in murine BV2 microglia cells and colitis mouse model." (PMID 38998493, 2024). "Treatment with L. casei IB1 improved DSS-induced colitis in mice, as indicated by increased body weight, colon length, and goblet cell numbers and decreased disease activity index (DAI), proinflammatory factor (TNF-α, IL-1β, and IL-6) levels, and histopathological scores after intake of IB1." (PMID 39065147, 2024). "EcN-TNFaNb and EcN-IL10 demonstrated effective mitigation of DSS-induced mouse colitis, as indicated by reduced colon length shortening, lower disease activity index (DAI), and altered expression of pro-inflammatory cytokines in colon tissues, such as TNF-α, IL-6, IL-17 A, and MCP-1." (PMID 38739270, 2024). "Importantly, TNF-α level in mice after ORMDL3 knockdown was similar to the DSS-sh-NT mice suggesting that ORMDL3 expression level did not affect TNF-α level during DSS-induced colitis." (PMID 38417794, 2024). "Furthermore, L. edodes polysaccharides have been shown to mitigate weight loss and reduce the expression of pro-inflammatory cytokines such as TNF-α, IL-6, IL-1β and IFN-γ in DSS-induced colitis in mice, suggesting their potential therapeutic efficacy in colitis treatment." (PMID 39130633, 2024). "In colitis mice, the percentage of MDSCs was positively correlated with colitis severity, and adoptive transfer of MDSCs could protect from TNBS-induced intestinal inflammation via the downregulation of IFN-γ, IL-17, and TNF-α." (PMID 37733169, 2024). "Abnormal immune responses in the gut are a feature of colitis, which is characterized by the increase of inflammatory cytokines (TNF-α, IL-1β, IL-6, etc) and decrease of anti-inflammatory cytokines, such as IL-10, and these changes are observed in patients with IBD and DSS-induced colitis mice." (PMID 37297494, 2023). "As in the updated European Crohn’s and Colitis Organisation (ECCO) recommendations, anti-TNF agents may be used on the basis of multidisciplinary decisions involving oncologists, taking into consideration current and recent IBD activity and alternative treatment options." (PMID 36831424, 2023).
colitis (continued). "Hence, 7 weeks after tofacitinib treatment was stopped, although T cells were capable of producing TNF, there were no mechanisms inducing this, since the colitis was mostly resolved." (PMID 37275854, 2023). "Interestingly, the cell state in the TNFα-treated wt organoids was similar to Mex3a positive cells, Lgr5 positive cells, and colitis cells, but not correlated with label-retaining cells (LRC) or other differentiated cells." (PMID 37845228, 2023). "In the DSS-induced colitis mouse model, oral administration of bioactive compounds of P. oleracea extract (portulacanone C, cis-n-feruloyl-3′-methoxytyramine, and trans-n-feruloyltyramine) and 3% DSS led to significant reduction of cytokine levels such as TNF-α, IL-6, 1L-1β, IL-4, IL-17, and IFN-γ." (PMID 37693918, 2023). "The qRT-PCR assays revealed that all serum IL-6, tumor necrosis factor α (TNF-α), and zonulin level at the mRNA levels significantly increased in the DSS-induced mice colitis relative to the WT group, which could be relieved by adding matrine in their drinking water (P < .05)." (PMID 37326155, 2023). "Notably, patients treated with a combination of anti-CTLA-4 and anti-PD-1 drugs who developed ICI-induced colitis overexpressed mucosal IL-1β (as well as IL-17), but not TNF-α, with a higher abundance of Bacteroides intestinalis." (PMID 36900420, 2023). "In a murine model of colitis, the previous and during-induction administration of CC-AST relieves colitis and significantly inhibits the expression of the inflammatory markers IL-1β, IL-6, TNF-α, cyclooxygenase-2, myeloperoxidase (MPO), iNOS, and NO in a more potent way than free AST." (PMID 37514016, 2023). "In fact, macrophage-derived TNFα does not contribute to somatic referred hyperalgesia, and might play a small role in colitis development and progression." (PMID 37049400, 2023). "Similarly, HS intake in mice resulted in an enhanced inflammatory response in terms of cytokine production (pro-inflammatory TNF-α, IL-17A, and IL-23), increased IL-23R+CD4 T cells, MAP, and exacerbated colitis in mice with artificially induced inflammatory bowel disease (IBD)." (PMID 37108475, 2023). "In addition, studies have reported that intraperitoneal injection of derivatives of oridonin at 5 mg/kg or 7.5 mg/kg in a mouse colitis model can improve colitis via reducing the expression of Th1/Th17, TNF-α, IFN-γ, and IL-17A and inhibiting the expression of NF-kB (p65), thereby improving colitis." (PMID 36894905, 2023). "Also, stimulation of canine MSCs with TNFα elevates TSG-6 and PGE2 resulting in in vivo benefit by regulating colonic inflammatory cytokines such as IL1β, IL6, and IL10, and ameliorating induced colitis in mice." (PMID 37275605, 2023). "Expression of NF-κB, TLR4, Myd88, and downstream molecules such as TNF-α, IL-6, and IL-1β was effectively reduced by SGP-H, which improved the secretion of anti-inflammatory cytokines including IL-20 and IL-10 in the colon tissue and serum of DSS-induced colitis mice." (PMID 37836386, 2023). "An interesting finding was that the reduction in the numbers of proinflammatory cytokines, such as TNF-α, IL-6, and IL-1β, as well as the increase in anti-inflammatory cytokines, such as IL-10, were increased significantly after treatment with GDENs in DSS-induced colitis." (PMID 38260737, 2023). "The results showed that colitis was dramatically ameliorated in the XJS-treated rats as evidenced by relief of clinical symptoms and histopathological damages, downregulation of pro-inflammatory cytokines IL-6, IL-17 and TNF-α, and upregulation of anti-inflammatory cytokine IL-10." (PMID 37153794, 2023). "These colitis mice also showed a shorter colonic length, increased colonic weight and index of colonic weight, DAI, and pathological damage score, as well as increased levels of pro-inflammatory cytokines TNF-α, IL-1β, IL-6, and IL-12p70, and decreased the level of anti-inflammatory cytokine IL-10." (PMID 36310616, 2022).
colitis (continued). "Sinomenine (at a dose of 100 or 200 mg/kg orally administered once daily for 7 days), a pure alkaloid isolated root of Sinomenium acutum, could decrease the level of miR-155 and TNF-α, and eventually ameliorate the histological score of colon tissue in TNBS-induced colitis of mice." (PMID 35493445, 2022). "Moreover, the same study found that the expression levels of TNF-α, IL-1β, and IL-12 in DSS-treated colitis mice increased drastically and were significantly, though only partly, reversed by transanal administration of heat-killed Levilactobacillus brevis SBC8803." (PMID 36558391, 2022). "Furthermore, VNS significantly improved the multivariate index of colitis in rats with TNBS-induced colitis and chronic VNS in the same model improved colitis and decreased the production of pro-inflammatory cytokines (TNF-α and IL-6)." (PMID 34983592, 2022). "Also nicotinic acid could inhibit the process of angiogenesis by changing the levels of TNF-α and VEGF to attenuate the severity of colitis." (PMID 35401181, 2022). "In addition, MAZ plays a crucial role in the transcription of inflammatory target genes, such as tumor necrosis factor α (TNF-α) and neutrophil chemokine Cxcl1, directly through activating the hypoxia-induced transcription factor (HIF-2a) in the progression of colitis hypoxia." (PMID 36358661, 2022). "DSS increases the production of pro-inflammatory mediators TNF-α, IL-1β, IL-6, IFN-γ and chemokine KC and macrophage inflammatory protein-2, which not only play important role in the pathogenesis of DSS-induced colitis, but also serve as crucial intervention targets for colitis." (PMID 36389828, 2022). "Exosomes from hucMSCs reduced the expression of the proinflammatory cytokines TNF-α, IL-1β and IL-6 in the colon in IBD mice, increased the expression of the anti-inflammatory cytokine IL-10 and attenuated the inflammatory response, thereby alleviating DSS-induced colitis in mice." (PMID 36045437, 2022). "However, unexpectedly, in our study, we did not observe a significant difference in TNF levels in the colon of colitis mice." (PMID 35295931, 2022). "It has been indicated that IL-1β could be a target for potential clinical intervention in patients with colitis who have not responded to the neutralization of TNFα." (PMID 36118873, 2022). "Therefore, over-expression of Zbtb7b might repress the differentiation of DP CD4+CD8+ T cells and then increase the production of inflammatory cytokines, such as TNF-α, IL-17, and IFN-γ, in the DSS-induced colitis model." (PMID 35761286, 2022). "Likewise, RvE1 facilitated tissue repair in peritonitis mice with TNBS-colitis, while significantly reduced the leukocyte infiltration, MPO activity, and the expression of genes corresponding to pro-inflammatory response (COX-2, TNF-α, IL-12p40, iNOS)." (PMID 35399093, 2022). "In this report, a 69-year-old male patient developed severe ICI-induced colitis 2 weeks after anti-PD-L1 mAb (i.e., durvalumab) treatment; unexpectedly failed to respond to systemic corticosteroid, anti-TNF, and anti-integrin agents; and unfortunately died in 1 month." (PMID 35814408, 2022). "TNFα levels were not different between normal control mice and colitis mice." (PMID 35741032, 2022). "In fact, glucosamine improved colitis symptoms in DSS-treated mice by preventing intestinal epithelial cell activation and tight junction proteins expression decrease, with a parallel decrease in the nuclear factor-kappa B (NF-kB) activity and reduced TNF-α and IL-1β release." (PMID 36009057, 2022). "Moreover, over-expression of Zbtb7b activated the maturation of CD4+T cells and repressed the differentiation of DP CD4+CD8+ T cells, which contributed to the production of inflammatory cytokines, such as TNF-α, IL-17, and IFN-γ, in the DSS-induced colitis model." (PMID 35761286, 2022).